BMI1 (BMI1 proto-oncogene, polycomb ring finger)
Diseases named in the same sentence as BMI1 in open-access papers (continued):
Sharing a sentence is not in itself a finding about the gene and the disease.
tumor (continued). "Nevertheless, in addition to shifting the balance in favor of epithelial gene programs, miR-200s have been found to negatively regulate self-renewal gene networks, by targeting BMI1 or SOX2 and thereby limiting the growth of normal and tumor cells." (PMID 29137351, 2017). "The development, proliferation and differentiation of tumor stem cells are related to several signaling pathways, such as Wnt/β-catenin, Wnt, Notch, HOX and Bmi-1 pathways." (PMID 28537906, 2017). "We showed that CSCs have significantly higher expression levels of BMI-1, MUC1-C, stemness proteins, signaling factors, and higher malignancy compared with normal tumor cells." (PMID 29299167, 2017). "Dr Singh’s lab has been studying the signalling pathways in the development of the tumour, such as the epigenetic regulator BM1, and the strategic Wnt activation of BMI1." (PMID 28275388, 2017). "The frequencies of cases showing high expression, which was defined as positive expression in>75% of tumor cells, were 55.2% (91/167) for EZH2, 32.3% (54/167) for SUZ12, 37.1% (62/167) for H3K27me3, and 31.1% (52/167) for BMI1." (PMID 28412742, 2017). "Bmi1, a polycomb‐group protein that maintains self‐renewal, is directly regulated by Twist1, which links EMT to tumor‐initiating ability." (PMID 28649800, 2017). "Inhibiting expression of the Bmi1 gene by stable transfection with shRNA to Bmi1 also inhibits proliferation of FMMC 419II cells in vitro and blocks tumor initiation." (PMID 28418883, 2017). "Phosphorylation by AKT at Ser 316 of BMI1, triggered its dissociation from the INK4A/ARF locus resulting in inability to promote tumor growth." (PMID 28270146, 2017). "Kreso and colleagues demonstrated that PTC-209 successfully inhibited the endogenous BMI-1 expression in human colorectal HCT116 and human fibrosarcoma HT1080 tumor cells." (PMID 27506934, 2016). "The stem cell markers DLG7 and BMI1 were significantly upregulated in CTC, indicating a stem cell-like phenotype and increased capacity of tumor formation and self-renewal." (PMID 27029058, 2016). "To determine the possible molecular mechanisms of the anti-tumor and inhibition of blood vessels role of Ad-Bmi-1i treatment, we examined the expression of p16 and p-AKT in control and Bmi-1 knockdown cells." (PMID 27009837, 2016). "Protein levels of ZEB2, BMI1, OCT4, and NANOG were decreased in tumor spheres compared to parental NPC cells." (PMID 27589832, 2016). "We observed that miR-203 overexpression modulated expression of EMT and tumor stemness factors including suppression of ZEB2, N-cadherin, NANOG, c-MYC, and BMI1 as well as induced E-cadherin expression." (PMID 27589832, 2016). "In prvious documents, BMI1 and SOX2 were the key tumor stemness factors, which had been documented as the direct targets of miR-200 family members." (PMID 27589832, 2016). "BMI1, EZH2 and other PcG proteins can be targeted by pharmacological inhibitors of HDACs, which are known for tumor suppressive properties." (PMID 27105531, 2016). "Our finding that BMI1 appears to contribute to chemoresistance in canine OSA cells is consistent with previous studies examining human OSA and other tumor cell lines." (PMID 26110620, 2015). "The observations from this study, that up-regulation of miR-128 inhibited HNSCC growth through directly mediating its targets Paip2, BAG-2, H3F3B, BMI-1, and BAX in proliferation and apoptotic pathways, support that miR-128 functions as a tumor suppressor." (PMID 25764126, 2015). "We observed a decrease in BMI1 protein expression in all three canine OSA cell lines following treatment of PTC-209 at 500nM, which is consistent with previous reports using human tumor cell lines." (PMID 26110620, 2015). "The relative expression of the genes Bmi-1, CCND1, and CDC6 was significantly increased in samples from all the tumor grades analyzed, and grade IV tumors were the most frequent." (PMID 26317630, 2015).
tumor (continued). "Here, we report that COX4-1 and BMI1 are co-expressed in highly proliferative human GBM tumors and highly enriched in tumor-initiating stem cells." (PMID 25726526, 2015). "MiR-203 has been reported as a novel tumor and metastasis suppressor by directly targeting mRNA of PLD2, Bmi-1 and PKCα." (PMID 25373785, 2014). "Subpopulations of tumor initiating cells from HNSCC are currently defined by their high expression of CD44 and BMI1 along with their high ALDH activity." (PMID 25471937, 2014). "Their loss, by releasing the inhibition upon tumor-promoting genes, such as BCL2, BMI1, CCND2 and CCND1, promotes cell growth and tumor progression." (PMID 24566314, 2014). "Hence, Bmi1 might be an ideal target to overcome chemoresistance and tumor relapse." (PMID 25348805, 2014). "In the present study, we found that knockdown of the Bmi1 gene inhibits HCC tumorigenicity and proliferation in vivo, both in the onset period and the fast growing period of the neoplasm." (PMID 25372945, 2014). "With pair-wise comparison of the whole genome gene expression profiles in FACS fractionated CD133+ and CD133− tumor cells, we showed that CD133+ and CD133− cells had distinct responsive genes following the silencing of BMI1." (PMID 25526772, 2014). "Nuclear expression of all individual markers (EZH2, BMI1, SUZ12 and H3K27me3) in tumor tissues was compared to nuclear expression in paired normal colorectal tissues." (PMID 25243792, 2014). "Among these chosen genes, p21 and p16 are recognized as crucial tumor suppressor genes, whereas BMI1 and c-MYC are important tumor promoting genes that can regulate expression of p21 and p16 as transcriptional factors." (PMID 23342141, 2013). "In our study, when Bmi1 expression was silenced in the CD44+CD24+ESA+ pancreatic CSC population, both in vitro CSC propagation and in vivo tumor growth were significantly inhibited." (PMID 23437065, 2013). "Using tumor cells other than CaP, we also showed that regulation of TCF4-mediated BCL2 by BMI1 is universal." (PMID 23671559, 2013). "We find that Bmi-1 activates the NF-κB signaling pathway and induces expression of NF-κB target genes, including VEGF-C that plays a pivotal role in tumor vascularization." (PMID 23383216, 2013). "The over-expression of Bmi-1 protein in UCC was apparently related to the distant metastasis (P<0.01) and the tumor, nodes and metastasis-classification, i.e. the TNM staging, World Health Organization (P<0.05)." (PMID 23691455, 2012). "IL-1β/TGF-β-induced neurospheres display up-regulated expression of stemness factor genes (nestin, Bmi-1, Notch-2 and LIF), and increased invasiveness, drug resistance and tumor growth in vivo: hallmarks of GSCs." (PMID 22330721, 2012). "5x105 Bmi-1-overexpressing ALDH1− cells significantly increased local invasion, distant metastasis to the lungs and tumor size compared with control ALDH1− cells." (PMID 20936121, 2011). "A recent study demonstrated that Bmi-1 mRNA and protein overexpressed in a subpopulation of tumor initiating cells in CD44+ HNSCC, which possessed self-renewal and tumor formation ability." (PMID 20936121, 2011). "Our data showed that ALDH1+ cells from HNSCC displayed higher levels of Bmi-1, and we further found that Bmi-1-silenced ALDH1+ cells showed increased sensitivity to radiotherapy and lower abilities for tumor invasion, colony formation, and self-renewal." (PMID 21461395, 2010). "We first examined Bmi-1 expression in ESCC cell lines and tumor samples by RT-PCR and Western blot analysis." (PMID 20809956, 2010). "LMP2A, Bmi-1 and ABCG2 transcripts were found to be low or undetectable in the 15 inflammatory samples but extremely high in the NPC tumor tissue." (PMID 20532215, 2010). "Immunofluorescent staining identified ∼30–40% of tumour spheroid cells expressing NES, BMI-1, and MSI-1." (PMID 20332776, 2010). "Inactivation of both Bmi1 and GSK3 depleted precursor cells required for tumor maintenance and progression." (PMID 19823589, 2009).
tumor (continued). "In order to evaluate Bmi1 function in NSCLC two founder lines that differ in incidence and latency of tumor formation were compared." (PMID 19156217, 2009). "Of note, tumours with both high EZH2 and BMI1 expression have a HR of 0.6 (95% CI = 0.3 to 1.2) compared with tumours that have high EZH2 and low BMI1, suggesting that the favourable effect of BMI1 overexpression is dominant over the adverse effects of EZH2." (PMID 19099573, 2008). "Microarray analysis of primary tumours shows that the Polycomb-group gene BMI1 is overexpressed in ERα-positive tumours (r = 0.62 for ESR1 versus BMI1, p = 4 × 10-7; similar results were obtained in several other microarray data sets)." (PMID 17573968, 2007). "We conclude that HMECs transduced with ERα, BMI1, MYC and TERT readily form oestrogen-dependent tumours in mice." (PMID 17573968, 2007). "For instance, BMI1-driven PI3K/Akt activation could attenuate FOXA1’s tumor-suppressive effects, thereby influencing tumor aggressiveness and therapeutic outcomes." (PMID 40623983, 2025). "Moreover, the xenograft tumor model showed that the increased tumor growth rate, consequent to FOXA1 knockdown, was significantly reversed by the knockdown of BMI1." (PMID 40623983, 2025). "Moreover, P. gingivalis-enhanced expression of SOX2, BMI1, and NANOG in tumor tissues were remarkably reduced by SCD1 knockdown." (PMID 40016182, 2025). "In the xenograft model, the co-knockdown of FOXA1 and BMI1 in CNE1 cells resulted in an increased sensitivity to cisplatin, as indicated by reduced tumor size and decelerated growth rates, in stark comparison to the FOXA1-knockdown cells that displayed resistance." (PMID 40623983, 2025). "Since Bmi‐1's major role is in remodeling the tumor niche to support the plasticity of GSCs rather than initiating the tumorous mass, we propose that silencing Bmi‐1 should be along with other treatment(s) to obtain the maximum benefit." (PMID 39791545, 2025). "In 65% of the cases, the BMI1 expression was high in tumor cells and did not significantly correlate with DFS, MFS, or OS." (PMID 40647395, 2025). "The enforced expression of Cirbp alone had little impact on the expression of stem cell-related markers (i.e., Nanog and Bmi-1) or slightly upregulated the expression of Sox2, Oct4 and ABCG2 in whole xenograft tumor lysates from CNE2 cells, as compared to those of control group (i.e., LV-con group)." (PMID 38419081, 2024). "The expression of BMI1, ITGB1, HISTH1B, PXN-AS1, and LOC100128361 in OCSCC tissues and adjacent tissues of 60 patients was detected by RT-qPCR, in which the expression of BMI1, ITGB1, and PXN-AS1 was significantly elevated in tumor tissues." (PMID 38254031, 2024). "Thus, we conducted quantitative assessments of the immunoexpression levels of CSC markers, including ALDH1, CD44, p75NTR, and BMI-1, along with E-cadherin, in both OSCC primary tumours and metastatic lymph nodes through the utilization of IHC." (PMID 38719848, 2024). "Interestingly, it has been demonstrated that Cisplatin-induced apoptosis mainly occurred in Bmi-1− tumor cells, and that in HNSCC recurrence specifically Bmi-1+ CSC lineages were maintained in these tumors." (PMID 36726797, 2023). "Notably, high levels of SOX2, BMI1, and CXCR4, as well as low levels of UBE2C in the tumor core (T) significantly correlate with a greater tumor size and lymph node compromise." (PMID 38096163, 2023).
tumor (continued). "Interestingly, when considering the CSC phenotype and plasticity in chemoresistant HNSCC tumor samples and cell lines, members of the regulator of embryonic stem cell Sox and Oct4 are highlighted over the classical CD44, Bmi1, and even ALDH1 CSCs biomarkers." (PMID 37065869, 2023). "In yet another example, Bmi-1-mediated tumorigenesis in liver cancer was not at all related to Ink4a/Arf expression but required for RasV12-driven tumor induction." (PMID 36726797, 2023). "Knockdown of KLF4 and BMI1 reduced the number and size of tumor sphere formation and tumor-initiating ability, suggesting that both KLF4 and BMI1 may contribute to inducing stem-like property and metastasis by TWIST1-JAGGED1-NOTCH-KLF4 signaling in HNC." (PMID 36553636, 2022). "Interestingly, squamous cell markers such as SALL4, NANOG, SOX2, BMI1, OCT3/4, HIWI, ABCG2, CD133, podoplanin, and ALDH1 also correlate with ESCC tumor stages, therapeutic resistance, relapse, and patient prognosis." (PMID 36474162, 2022). "We further demonstrated that BMI1/RAD51 axis activation is necessary to prevent cisplatin-induced DNA damage and that treatment of patient-derived xenografts with a RAD51 inhibitor sensitizes tumor-initiating cells to cisplatin." (PMID 35110528, 2022). "BMI1 specific inhibition pharmacologically or genetically was capable of eliminating CSC BMI1 + and leads to cellular immune activation against the tumor in addition to improvement of anti-PD-1 therapy, achieving inhibition of tumor growth, spread, and relapse." (PMID 35982868, 2022). "Of note, the transient inhibition of BMI1 in tumour with small molecules would not be comparable to the genetic ablation of BMI1 in tissue cells in transgenic mice as presented in those studies." (PMID 35794816, 2022). "Following on from the evidence of a CHD7-BMI1-MAPK regulatory axis in MB cells, we set out to assess whether BMI1 and MAPK inhibitors could be used in combination to potentiate their anti-tumor activity." (PMID 35213723, 2022). "Bmi-1 has been found to contribute to laryngeal squamous cell carcinoma (LSCC) progression and maintain tumorigenic laryngeal growth, suggesting that miR-128 plays a tumor suppressor role in laryngeal cancer." (PMID 36793341, 2022). "In this study, although BMI1 was not upregulated in tumor tissues when compared to adjacent normal tissues, however, its upregulation was observed at stages I and II of CRC relative to the control samples." (PMID 35845311, 2022). "Significantly, AMP-depleted tumour-derived cells obtained after BT-474 injection into mice showed a reduction in NANOG, OCT4 and BMI1 gene expression, providing evidence that AMPK can also drive transcriptional upregulation and maintenance of stemness markers in the in vivo tumour microenvironment." (PMID 35195687, 2022). "Finally, BMI1 itself is a component of the PRC1-repressing complex, and acts together with the PRC2 complex to repress the promoter of tumor suppressor-related genes to enhance the CSCs phenotype." (PMID 35159370, 2022). "The MKK3 tumor-suppressing role depended on Bmi-1 downregulation and p38MAPK activation, as the SB203580 rescued Bmi-1 expression downregulating p16 INK4A and p15 INK4B to normal levels and suppressing the MKK3-induced cell cycle arrest in HepG2 and PLC-PRF-5 cells." (PMID 35158751, 2022). "Therefore, further regulatory mechanisms of Bmi-1-promoting CSC need to be revealed, and its role in tumor promotion requires exploration, to provide new therapeutic strategies for anti-tumor therapy." (PMID 35897796, 2022). "Notably, we found that YTHDC1 mRNA expression levels were significantly and positively correlated with those of BMI1 and SOX2, which are HNSCC tumor stem cell-specific indicators." (PMID 36411870, 2022).
tumor (continued). "The HH and Wnt pathways can jointly induce CSC biomarkers, such as CD44, CD133, BMI1, and LGR5, and promote EMT, thereby promoting tumor cell infiltration and distant metastasis and allowing tumor cells to obtain stem cell characteristics and drug resistance capacity." (PMID 35719973, 2022). "Among these target genes, we focused on a tumor suppressor, SIK1, and sought to determine whether BMI1 directly regulates SIK1 transcription." (PMID 35346195, 2022). "A dual staining assay for CD44 and BMI-1 demonstrated that there was an elevated expression of CD44 and BMI-1 in the TRAMP prostates which was considerably downregulated by IP6 treatment across all tumor stages." (PMID 36077751, 2022). "Although the tumour‐suppressor p16INK4A is a well‐documented target of BMI1‐induced gene silencing, knockdown of BMI1 did not significantly change p16INK4A expression either in mRNA or protein level in our study." (PMID 35794816, 2022). "Furthermore, BMI1’s oncogenic activity displays a relationship with PTEN (phosphatase and tensin homolog), a well-established tumour suppressor." (PMID 33804165, 2021). "Moreover, abnormal activation of AP-1 plays a critical role in Bmi-1+ CSC-mediated HNSCC invasive growth, and targeting the tumor bulk and Bmi-1+ CSCs by combination therapy effectively inhibits HNSCC growth and eliminates metastases." (PMID 34689153, 2021). "Similarly, we observed that si-BMI1, si-KLF4, combination therapy, and PTC-209 all significantly inhibited tumor cell invasion compared with each control group (*p < 0.05; **p < 0.01)." (PMID 33828977, 2021). "Tumor samples of 40 consecutive patients with adenocarcinoma of the major salivary gland treated with curative intend at one tertiary center were stained with the CSCs ALDH1, BMI-1, CD44, Nanog, and SOX2." (PMID 33009929, 2021). "To determine whether the expression of LSD1 and Bmi-1 is correlated in HNSCC, we examined their expression in multiple HNSCC cell lines and tumor specimens." (PMID 34689153, 2021). "In prostate cancer, for example, BMI1 (PCGF4) binds to the androgen receptor (AR) independently of the PRC1 complex thereby preventing protein degradation, which results in sustained AR signalling promoting tumour growth." (PMID 34316702, 2021). "Recently, downregulation of BMI1 in mouse BCSC line FMMC 419II by the inhibitor, PTC 209, and a stable transfection with a BMI1 shRNA plasmid, correlated with reduced mammosphere formation and a decrease in tumor mass." (PMID 34360879, 2021). "RNF220 regulated BMI1 expression through USP22, promoting tumor growth in vivo." (PMID 34753387, 2021). "Similarly, in squamous cell carcinoma (SCC) TWIST is regulating BMI1 to cooperatively repress CDKN2A (p16INK4A) and promote tumor initiation capacities." (PMID 34459003, 2021). "In addition, the ability of 786-O cells to generate tumor spheres was enhanced and the protein expression of CD133, Bmi-1, SOX-2 were upregulated under the culture with ox-LDL." (PMID 33935779, 2021). "Finally, ZEB1, BMI1, and ALDH1A1 were highly expressed in tumor specimens from EGFR‐mutant NSCLC patients with gefitinib resistance." (PMID 33764690, 2021). "GANT61 treatment significantly decreased BMI1 and SOX2 expression in vivo in tumor xenografts." (PMID 33499351, 2021). "In lung cancer models, HOTAIR could activate BMI1, CD44, OCT4, and CD133, whose expression is critical for tumor cell reprogramming toward a CSC phenotype." (PMID 32932969, 2020). "At 16 weeks of 4NQO treatment, Bmi1+ cells underwent apoptosis caused by diphtheria toxin after tamoxifen injection, resulting in almost no Bmi1+ cells in the tumor." (PMID 32884573, 2020). "We report here that when used at appropriate concentrations, pharmaceutical inhibitors of BMI1 could efficiently prevent GBM colony growth and CSC self-renewal in vitro and significantly extend lifespan in terminally ill tumor-bearing mice." (PMID 31934644, 2020).